MYO1B (myosin IB)
Description:
Motor protein that may participate in process critical to neuronal development and function such as cell migration, neurite outgrowth and vesicular transport.
Synonyms: MMI-alpha; MMIa; myr1; MYH-1c
Tractability: Antibody: its Gene Ontology location is reachable by antibodies, with high confidence; the Human Protein Atlas places it where antibodies can reach. PROTAC: UniProt records ubiquitination sites on it; ubiquitination databases record sites on it; its protein half-life has been measured.
Gene: Protein-coding gene on chromosome 2 (191,245,064 to 191,425,820, forward strand). Ensembl gene ENSG00000128641.
Subcellular location (Human Protein Atlas): Plasma membrane
Gene Ontology:
Molecular function: actin filament binding; ATP binding; cadherin binding; microfilament motor activity; protein binding; phosphatidylinositol-3,4,5-trisphosphate binding; phosphatidylinositol-4,5-bisphosphate binding; cytoskeletal motor activity
Biological process: actin filament organization; post-Golgi vesicle-mediated transport; actin filament bundle assembly; actin filament-based movement; endocytosis
Cellular component: actin filament; early endosome; endosome membrane; extracellular exosome; perinuclear region of cytoplasm; plasma membrane; trans-Golgi network membrane; actin cytoskeleton; brush border; cell periphery; cytoplasm; filopodium; microvillus; myosin complex
Genetic constraint (gnomAD): Loss-of-function variants: 55 observed, 124.25 expected, observed/expected ratio (o/e) 0.44, 90% interval 0.35 to 0.55. The upper end of that interval is the gene's LOEUF score, 0.55, which puts it in group 2 of 6, group 1 being the genes least tolerant of losing a copy. Missense variants: 908 observed, 1,217.4 expected, observed/expected ratio (o/e) 0.75, 90% interval 0.7 to 0.79. Synonymous variants: 410 observed, 433.97 expected, observed/expected ratio (o/e) 0.94, 90% interval 0.87 to 1.02.
Homologues: Orthologues: chimpanzee MYO1B (100% identical), macaque MYO1B (99% identical), dog MYO1B (99% identical), pig MYO1B (98% identical), guinea pig MYO1B (98% identical), mouse Myo1b (98% identical), rat Myo1b (97% identical), rabbit MYO1B (97% identical), zebrafish myo1b (80% identical). Paralogues in human: MYO1A (54% identical), MYO1C (40% identical), MYO1H (38% identical), MYO1D (36% identical), MYO1G (34% identical), MYH10 (29% identical), MYO7B (29% identical), MYO7A (29% identical), MYH9 (28% identical), MYH3 (28% identical), MYH6 (28% identical), MYH7 (28% identical), and 32 more.
Diseases named in the same sentence as MYO1B in open-access papers:
MYO1B is named in the same sentence as 42 diseases in open-access papers, as found by Europe PMC text mining. Sharing a sentence is not in itself a finding about the gene and the disease. The quoted sentences say what the papers report.
colorectal cancer (7 papers, 2015 to 2025). A primary or metastatic malignant neoplasm that affects the colon or rectum. "Through literature research, we found that MYO1B is associated with the development of various malignancies and enhances tumor cell migration and invasion in colorectal cancer by activating the RhoA/ROCK/FAK signaling pathway." (PMID 41278212, 2025). "In intestine Myo1a regulates polarization and differentiation of colorectal cancer cells, is mutated in colorectal cancers, and has tumor-suppressor activity suggesting that equally important physiological roles for Myo1b in humans will ultimately be found." (PMID 26361046, 2015). "Specifically, the expression of MYO1B has been found in various cancer types, such as colorectal cancer and cervical cancer, where it contributes to cell migration, invasion, and metastasis." (PMID 39768999, 2024). "Recently, MYO1B was reported to aggravate colorectal cancer metastasis via enhancing rearrangement of F-actin and focal adhesion assembly mainly through targeting RhoA." (PMID 35478939, 2022). "Previous researches revealed that MYO1B expression levels were elevated in cervical cancer, prostate cancer, colorectal cancer, and oral tongue cancer." (PMID 35478939, 2022). "Furthermore, other members of the class I myosin family, such as MYO1B and MYO1E, have been associated with poorer survival outcomes in colorectal cancer and lung adenocarcinoma, respectively." (PMID 39205690, 2024). "Collectively, these results suggest that the expression of Myo1b is enhanced in colorectal cancer, and it might play a crucial role in tumor progression." (PMID 36347835, 2022).
prostate carcinoma (7 papers, 2015 to 2023). A carcinoma that arises from epithelial cells of the prostate gland. "MYO1B has been reported to promote tumorigenesis and metastasis in cancers such as prostate cancer, cervical cancer, glioblastoma, and head and neck squamous cell carcinoma." (PMID 37611092, 2023). "Myo10 and Myo1b are both expressed at higher levels in prostate cancer cells with high metastatic potential and in metastatic prostate cancer tissues." (PMID 35853101, 2022). "MYO1B is expressed at high levels in prostate cancer tissues, head and neck squamous cell carcinoma (HNSCC), and melanoma." (PMID 32670437, 2020). "Our previous studies revealed that tumor-suppressive miR-145-3p was closely involved in human cancer pathogenesis by targeting oncogenes, for example, MTDH in LUSQ; MELK, NCAPG, BUB1, and CDK1 in prostate cancer; MYO1B in head and neck cancer; and MYO1B and DHRS2 in esophageal cancer." (PMID 31514295, 2019). "Knocking down MYO1B expression in PC-3 (prostate cancer-3) cells can increase their diffusion area and induce the formation of long and sparse stress fibers, which is speculated to be consistent with the partial reorganization of cortical actin into stress fibers." (PMID 32670437, 2020). "In the current study, quantitation of gene signatures for the early endosomal genes APPL1, EEA1 and RAB5A, and analysis of the endosomal genes MYO1B, PDCD6IP and STX12 in prostate cancer patients expressing PSA ≤ 10 ng/mL, led to patient stratification into high and low-risk recurrence groups." (PMID 26473288, 2015).
head and neck squamous cell carcinoma (6 papers, 2020 to 2024). A squamous cell carcinoma that arises from any of the following anatomic sites: lip and oral cavity, nasal cavity, paranasal sinuses, pharynx, larynx, and salivary glands. "Epigenetic alteration of miR-145-3p and miR-363 was found to control the expression of the MYO1B gene in head and neck squamous cell carcinoma, which, in turn, led to increased migration and invasion of cancer cells." (PMID 39768999, 2024). "Recently, aberrant expression of Myo1b has been detected in various cancers, including prostate cancer, head and neck squamous cell carcinoma (HNSCC), cervical cancer, esophageal squamous cell carcinoma (ESCC) and glioma." (PMID 36347835, 2022). "Myo1b over expression has been reported in head and neck squamous cell carcinomas (HNSCC)." (PMID 34974807, 2022).
breast carcinoma (5 papers, 2015 to 2025). "SRSF1 regulates the alternative splicing of MYO1B gene and inhibits its protein level, thereby inhibiting the proliferation, metastasis and stem cell properties of breast cancer cells, and promoting the chemosensitivity of drug-resistant breast cancer cells." (PMID 40176901, 2025). "Knockdown of SRSF1 can reduce the expression level of full-length MYO1B protein in both drug-resistant and parental breast cancer cells, indicating that SRSF1 regulated the alternative splicing of MYO1B in breast cancer cells." (PMID 40176901, 2025). "Targeting SRSF1 or MYO1B may be identified as a novel molecular mechanism to against drug resistant in breast cancer." (PMID 40176901, 2025). "In conclusion, CYT repressed the growth and metastasis of BC cells and recovered drug sensitivity, through SRSF1-regulated the alternative splicing of MYO1B RNAs, which may represent a novel molecular mechanism to overcome drug resistance in breast cancer." (PMID 40176901, 2025). "Thus, the development of small-molecule inhibitors or modulators targeting SRSF1 or MYO1B may provide a novel therapeutic strategy for drug-resistant breast cancer." (PMID 40176901, 2025). "Our findings identified the effects of CYT on identifying the potential regulatory with SRSF1/MYO1B axis via transcriptome analysis and experiment verification, supporting the anti-tumor effects of CYT against drug resistant breast cancer." (PMID 40176901, 2025). "In this study, we identified the effects of CYT on overcoming drug resistance of breast cancer and identified the potential regulatory with SRSF1/MYO1B axis via transcriptome analysis and experiment verification." (PMID 40176901, 2025). "Notably, our data indicate that by targeting SRSF1-mediated alternative splicing of MYO1B, CYT can inhibit the chemo-resistance of breast cancer." (PMID 40176901, 2025).
glioma (5 papers, 2022 to 2025). A benign or malignant brain and spinal cord tumor that arises from glial cells (astrocytes, oligodendrocytes, ependymal cells). "For example, alterations in alternative splicing of the PKM, ANAX7, and MYO1B genes have been implicated in the context of glioma progression." (PMID 36171198, 2022). "In conclusion, our study elucidates mechanism that SNHG4 promotes progression of glioma through miR-367-3p/MYO1B axis, which may contribute to find the potential diagnostic and therapeutic target of glioma patients." (PMID 39951205, 2025). "Mechanically, SNHG4 participated in the progression of glioma through the miR-367-3p/MYO1B axis, which was a novel signaling pathway of SNHG4." (PMID 39951205, 2025). "To investigate that SNHG4 plays roles in the progression of glioma through MYO1B-regulated pathway, we first detected the expression of MYO1B after knocking down SNHG4 in Ln229 and U251 cells in mRNA and protein levels by qRT-PCR and western blot assays." (PMID 39951205, 2025). "Our study reveals that SNHG4 promotes the proliferation, migration of glioma via regulating miR-367-3p/MYO1B axis." (PMID 39951205, 2025). "Rescue assays showed that knockdown of SNHG4 inhibited glioma cell proliferation, migration, while the inhibitory effects were impaired by inhibiting miR-367-3p or overexpression of MYO1B." (PMID 39951205, 2025). "In line with our findings, previous studies have shown that SRSF1 was increased in gliomas, which promoted gliomagenesis via guided alternative splicing of the MYO1B gene, leading to activation of PDK1/AKT and PAK/LIMK signaling pathways." (PMID 37063420, 2023). "For example, the splice switch of MYO1B directly regulated by SRSF1 increased the carcinogenic potential of glioma cells through the PDK1/AKT and PAK/LIMK pathways." (PMID 37667311, 2023). "The SNHG4/miR-367-3p/MYO1B axis might provide a novel approach for the treatment of glioma patients, which might be used as the potential prognostic and therapeutic biomarkers." (PMID 39951205, 2025). "Furthermore, the rescue experiments showed that the inhibition of miR-367-3p or the expression of MYO1B partially rescue the inhibition effects of SNHG4 in glioma cells." (PMID 39951205, 2025). "In conclusion, the miR-367-3p/MYO1B axis regulates the progression of glioma cells." (PMID 39951205, 2025). "The rescue experiments of cell proliferation proved that the inhibitory effects arising by the miR-367-3p mimics in glioma cells could be alleviated by the overexpression of MYO1B in Ln229 and U251 cells." (PMID 39951205, 2025). "Then, we investigated whether miR-367-3p could involve in glioma cell proliferation and migration through MYO1B." (PMID 39951205, 2025). "Furthermore, SRSF1 promotes cell proliferation, survival, and invasion in glioma tissues and cell lines by specifically switching the AS of myosin IB (MYO1B)." (PMID 36882745, 2023).
melanoma (4 papers, 2014 to 2025). A malignant, usually aggressive tumor composed of atypical, neoplastic melanocytes. "The opposing effect of MYO1B on cell apoptosis in senescent vascular smooth muscle cells and melanoma cells suggest its dual role in the regulation of apoptosis through different mechanisms in different cells and circumstances." (PMID 31349190, 2019). "Moreover, the elevated nuclear PTEN upon silencing MYO1B promotes apoptosis of MEFs and melanoma B16F10 cells." (PMID 31349190, 2019). "Targeting MYO1B may represent a therapeutic approach for cancer treatment such as melanoma." (PMID 31349190, 2019). "Notable findings include NRAS Q61L melanomas being enriched for modules involving C19orf10 and ARF4, while BRAF V600E melanomas were enriched for modules involving ALAS1 and MYO1B." (PMID 39796775, 2025). "We next wish to investigate the effects of MYO1B-mediated prevention of PTEN nuclear localization on cell apoptosis in immortalized MEFs and melanoma cells." (PMID 31349190, 2019). "In support of previous reports, silencing MYO1B, which augmented nuclear PTEN level, induced cell apoptosis of MEFs and melanoma cell B16F10 as reflected by enhanced Annexin-V immunostaining and increased cleaved caspase 3 level without a change in PCNA level." (PMID 31349190, 2019). "However, PSAP, MYO1B and BUB3 seem to follow the same trend as shown by proteomics analysis in all three melanoma cell lines." (PMID 24743044, 2014). "Regarding the role of MYO1B in cell apoptosis, it promotes apoptosis in senescent cells through ARG2-induced over-activation of MTORC1-RPS6K1 signaling, whereas it antagonizes apoptosis by preventing nuclear accumulation of PTEN in immortalized cells and tumor cells such as melanoma." (PMID 31349190, 2019).
cervical cancer (3 papers, 2022 to 2024). A primary or metastatic malignant neoplasm involving the cervix. "For instance, MYO1B was illustrated to contribute to cell proliferation, migration, and invasion and enhanced the activities of MMP1/MMP9 in cervical cancer." (PMID 35478939, 2022).
head and neck cancer (3 papers, 2015 to 2022). A primary or metastatic malignant neoplasm affecting the head and neck. "Taken together, these studies reveal that miR-363 binding site 1 (chr2:192,288,731-192,288,738) plays a functionally significant role in the regulation of MYO1B expression by this miRNA in head and neck cancer cell lines." (PMID 26545583, 2015).
esophageal squamous cell carcinoma (2 papers, 2022). Esophageal squamous cell carcinoma (ESCC) is a type of esophageal carcinoma (EC) that can affect any part of the esophagus, but is usually located in the upper or middle third. "Myo1b is also overexpressed in Esophageal Squamous Cell Carcinoma (ESCC) clinical samples, in this cancer Myo1b is associated with cancer cell aggressiveness and metastasis, downstream genes controlled by Myo1b includes MMP1/13 both of which are highly expressed in ESCC clinical specimens." (PMID 34974807, 2022).
oral cancer (2 papers, 2025). "Recent studies have identified MYO1B as a key gene in oral cancer, with its overexpression being associated with lymph node metastasis and unfavorable outcomes." (PMID 40818124, 2025). "Suppression of MYO1B can inhibit the proliferation, invasion, and metastasis of oral cancer cells, making it a potential therapeutic target for oral cancer." (PMID 40818124, 2025).
pancreatic cancer (2 papers, 2015 to 2019). "(A) Based on the GENT database, LASP1, RAB11B, RUVBL1 and MYO1B gene expression were analyzed in the pancreatic cancer tissues and normal pancreatic tissues." (PMID 31395079, 2019). "Based on the GENT database, we showed that both LASP1 and RUVBL1 gene expression were significantly upregulated in pancreatic cancer tissues compared with that in normal pancreatic tissues, while RAB11B was not changed obviously, and MYO1B was significantly downregulated." (PMID 31395079, 2019).
age (1 paper, 2023). A temporal measurement of the time period elapsed since an identifiable point in the life cycle of an organism. "This represents another novel mechanism of that Myo1b regulates endothelial aging and a promising therapeutic approach to target vascular aging and age-associated cardiovascular diseases." (PMID 36654782, 2023).
brain tumor (1 paper, 2023). "To further validate our finding that MNA+ cancers may deploy a GREB1-dependent mechanism to drive expression of pro-oncogenic genes such as MYO1B, independently of MYCN, we investigated medulloblastoma (MB), a childhood brain tumor that also harbors recurrent MNA." (PMID 37611092, 2023).
diabetic nephropathy (1 paper, 2023). "Finally, both SYNE1 and MYO1B have been described as related to diabetic nephropathy before." (PMID 36769128, 2023).
endothelial dysfunction (1 paper, 2023). In vascular diseases, endothelial dysfunction is a systemic pathological state of the endothelium (the inner lining of blood vessels) and can be broadly defined as an imbalance between vasodilating and vasoconstricting substances produced by (or acting on) the endothelium. "In vitro and in vivo aging models, Myo1b knockdown in senescent ECs and wild type-aged mice is able to enhance autophagy and ameliorate aging-associated endothelial dysfunction." (PMID 36654782, 2023). "Overall, the results from the cultured cells and mouse model provide both in vitro and in vivo firm evidence for a causal role of Myo1b in promoting endothelial inflammation, endothelial dysfunction, and vascular aging." (PMID 36654782, 2023). "Silencing Myo1b in these senescent ECs not only restores the senescence-associated autophagic flux but also improves the senescence-associated endothelial dysfunction." (PMID 36654782, 2023). "Indeed, Myo1b knockdown in the old mice significantly improves the aging-induced endothelial dysfunction with the concomitant elevation of vascular autophagy, suggesting the causal role of Myo1b-associated autophagy impairment in cardiovascular aging in vivo." (PMID 36654782, 2023). "Here, we find that Myo1b promoting young EC senescence, endothelial dysfunction, and inflammation is accompanied by the impairment of the autophagosome-lysosome fusion, which is reversed by the rapamycin that promotes autophagosome-lysosome fusion." (PMID 36654782, 2023). "This conclusion is further reinforced by experiments of overexpressing Myo1b in young ECs showing that it significantly drives young cell senescence and endothelial dysfunction and SASP." (PMID 36654782, 2023). "In this study, we, for the first time, identified that Myo1b as a novel regulator of EC senescence mediates endothelial dysfunction with a link to vascular aging through the suppression of endothelial autophagy." (PMID 36654782, 2023). "Interestingly, we observed that the senescence (SA-β-gal-stained positive cells) and endothelial dysfunction, i.e., overproduced superoxide and reduced NO levels, provoked by Myo1b were significantly reversed by rapamycin." (PMID 36654782, 2023). "Meanwhile, upon the overexpression of Myo1b, the young HUVECs tended to accelerate the senescence evaluated by the augmented number of SA-β-gal positive cells and the occurrence of endothelial dysfunctions, e.g., the impaired NO production (DAF-2DA) and enhanced intracellular superoxide production." (PMID 36654782, 2023).
Hyperkeratosis (1 paper, 2022). Hyperkeratosis is a histopathological term defining a thickened stratum corneum and may be present in many different skin conditions, with many possible overlaps. "Among these genes, SQLE, STRN, EIF4, and MYO1B expression was increased in patients with hyperkeratosis, parakeratosis, and acanthosis thickening." (PMID 35277199, 2022). "Patients with hyperkeratosis and parakeratosis, acanthosis thickening had increased expression of 13 the same genes, including SQLE, STRN, EIF4E, and MYO1B." (PMID 35277199, 2022). "Therefore, we speculate that AP-1 upregulates the expression of SQLE, STRN, EIF4E, and MYO1B; it brings keratinocytes EMT, which further mediates hyperkeratosis with parakeratosis and acanthosis thickening." (PMID 35277199, 2022).
lung carcinoma (1 paper, 2021). "In reports on radiotherapy for lung cancer, the binding site regulated by SRSF1 was TTACCAGTAA, and another report predicted and verified that the binding motif of SRSF1 derived from RNA-seq to regulate the AS of MYO1B is GAGGGG." (PMID 33992102, 2021).